ENO2 (enolase 2)
Diseases named in the same sentence as ENO2 in open-access papers (continued):
Sharing a sentence is not in itself a finding about the gene and the disease.
gastric cancer (13 papers, 2017 to 2026). A primary or metastatic malignant neoplasm involving the stomach. "In addition to HK2, METTL3 promotes expression of enolase 2 (ENO2), an enzyme that dehydrates 2-phsophoglycerate to phosphoenolpyruvate, in gastric cancer." (PMID 36289851, 2022). "The secreted HDGF induced tumor angiogenesis, while nuclear HDGF activated glucose transporter type 4 (GLUT4) and enolase-2 (ENO2) expression, followed by an elevation in glycolysis in gastric cancer cells, which was correlated with subsequent tumor growth and liver metastasis." (PMID 34774047, 2021). "PELI2, RGS2 and ENO2 has been poorly reported in relation to liver cancer, whereas PELI2 involved in 28 gene expression characteristics can well predict gastric cancer with lymphatic metastasis." (PMID 37397026, 2023). "Previous studies indicated that in human gastric cancer cells, high expression of METTL3 stimulates the expression of GLUT4 and ENO2 via the METTL3/HDGF axis, thereby promoting tumor angiogenesis and glycolysis." (PMID 36347025, 2022). "HDGF in turn functions as a transcriptional regulator that binds to the promoter region of ENO2 and GLUT4 to promote their transcription and expression in gastric cancer cells." (PMID 36289851, 2022). "In addition, upregulation of METTL3 in gastric cancer promotes tumor angiogenesis and glycolysis by promoting IGF2BP3-dependent hepatoma-derived growth factor (HDGF) mRNA stability, which is essential for increasing in glycolysis by activating GLUT4 and ENO2 in gastric cancer cells." (PMID 34616742, 2021).
glioblastoma (13 papers, 2011 to 2025). The most malignant astrocytic tumor (WHO grade IV). "The glycolytic gene enolase 1 (ENO1), located on chromosome 1p36, is deleted in approximately 5% of glioblastoma patients, with ENO2 compensating for its loss." (PMID 40552664, 2025). "This was demonstrated in glioblastoma when it was observed that inhibition of ENO2 was selectively toxic to ENO1 deficient glioblastoma cells." (PMID 26579514, 2015). "The glycolytic gene ENO1 in the 1p36 locus is deleted in approximately 5% of glioblastoma patients, which is compensated by expression of ENO2." (PMID 33401771, 2021). "Recently, human enolase 2 (ENO2) phosphonate inhibitors have been developed as lead agents to treat glioblastoma multiforme (GBM)." (PMID 39088549, 2024). "This makes ENO2 a promising therapeutic target, and indeed, ENO2 inhibition by knockdown selectively suppressed the growth and tumorigenic potential of ENO1‐deleted glioblastoma cells." (PMID 40552664, 2025). "Therefore, ENO2 inhibition selectively suppresses the growth, survival, and tumorigenic potential of ENO1-deleted glioblastoma cells." (PMID 33401771, 2021).
Anxiety (11 papers, 2009 to 2026). Intense feelings of nervousness, tension, or panic often arise in response to interpersonal stresses. "Our mouse model, using an Emx1-Cre to ablate Miro1, displays distinct anxiety-like behavior patterns that are distinct from those observed in previous models such as when Miro1 is removed using the Eno2-Cre." (PMID 41386992, 2026). "In order to analyze whether the observed phenotype was due to the expression of the ΔGR we studied anxiety-related behavior in the EPM in three month-old Eno2-ΔGR/EGFP bigenic mice, i.e. before these mice expressed the ΔGR transgene." (PMID 19888328, 2009). "We extended these studies by analyzing the behavior of Eno2-ΔGR/EGFP bigenic mice in the emergence test which is also widely used to analyze anxiety-related behavior." (PMID 19888328, 2009). "Taken together these results indicate that Eno2-ΔGR/EGFP bigenic mice have an increase in stress-related behavior and in particular in behaviors suggesting higher anxiety and despair induced by aversive situations." (PMID 19888328, 2009). "Eno2-ΔGR/EGFP bigenic mice had significantly longer latencies before emerging from the protective cylinder, indicating higher anxiety when faced with the threatening open field (t21 = −3.706 p<0.0014)." (PMID 19888328, 2009).
neuropathy (10 papers, 2015 to 2025). A disorder affecting the nervous system that manifests with pain, tingling, numbness, and/or muscle weakness. "Circulating ENO2/NSE mRNA levels were lower in diabetics with neuropathy (mean HbA1c = 8.2%) than in those without neuropathy (mean HbA1c = 6.6%)." (PMID 28812028, 2017).
colon cancer (9 papers, 2008 to 2025). "ENO2 (alpha-enolase) is significantly upregulated in a metastatic colon cancer cell line, suggesting a possible association with the metastatic process in vitro and in vivo." (PMID 30967137, 2019). "Indeed, ENO2 is upregulated in a variety of cancers and alpha-enolase is significantly upregulated in a metastasic colon cancer cell line, suggesting a possible association with the metastasic process in vitro and in vivo." (PMID 18694510, 2008). "Previous studies found that enolase 2 (ENO2) is an essential glycolytic enzyme in the metabolic process of glycolysis, whereas its roles in colon cancer are still unclear." (PMID 35778964, 2023). "The positive correlation between PPFIA4 and ENO2/PFKFB3 levels also corroborated that PPFIA4 was a potential regulator of glycolysis in colon cancer." (PMID 34094943, 2021). "Additionally, RT-PCR confirmed the association of CUL7, ENO2, and MPP2 expression levels with colon cancer." (PMID 40260289, 2025). "Thus, we decided to search for other differentially expressed genes (CAV1, E-cadherin, ENO2 and PKCα) that had been previously related with resistance or with colon cancer and to evaluate their relative contribution in our cell system." (PMID 18694510, 2008). "CUL7, ENO2, and MPP2 were identified as potential antigens for colon cancer mRNA vaccines, with MPP2 showing particular immunological relevance." (PMID 40260289, 2025). "Particularly, we demonstrated that BRD9 mediates the enrichment of H3K27ac at ENO2 and ALDOC gene loci, thereby enhancing the glycolytic activities of colon cancer cells." (PMID 35778964, 2023). "We first analyzed the correlation between PPFIA4 and two glycolysis-related genes, ENO2 (enolase 2) and PFKFB3 (6-Phosphofructo-2-Kinase/Fructose-2,6-Biphosphatase 3), in the TCGA colon cancer database." (PMID 34094943, 2021). "Thus, This study identifies CUL7, ENO2, and MPP2 as potential antigens for colon cancer mRNA vaccines." (PMID 40260289, 2025).
diabetic neuropathy (9 papers, 2018 to 2025). A chronic, pathological complication associated with diabetes mellitus, where nerve damages are incurred due to diabetic microvascular injury involving small blood vessels that supply these nerves, resulting in peripheral and/or autonomic nerve dysfunction. "A slight increase in plasma enolase-2 concentration has been reported in T2DM patients, and it was concomitantly enhanced in patients with diabetic neuropathy." (PMID 40149589, 2025).
metastatic disease (9 papers, 1992 to 2026). "We found that ENO2 expression was significantly higher in metastatic tumors than in primary tumors." (PMID 35954207, 2022).
schizophrenia (9 papers, 2008 to 2025). A major psychotic disorder characterized by abnormalities in the perception or expression of reality. "Proteomics analysis of post mortem brains of patients with schizophrenia showed alterations in the levels of energy metabolism-associated proteins, such as aldolase C (ALDOC), enolase 2 (ENO2), and glyceraldehyde-3-phosphate dehydrogenase (GAPDH)." (PMID 30890939, 2019). "Recent studies have identified ENO2 as a gene involved in the development of autism; differential expression of the ENO2 gene in the Wernicke area in patients with schizophrenia and in the anterior cingulated cortex in female schizophrenia patients." (PMID 24737292, 2014). "As we cannot draw firm conclusions with the current data further investigations with testing of more loci are required to clarify whether ENO2, FBP1, MAPK14 and PCK1 variants provide genetic support for the view that alterations in glucose metabolism are intrinsic to schizophrenia etiology." (PMID 18460190, 2008).
Obesity (7 papers, 2015 to 2025). Accumulation of substantial excess body fat. "For DE RNAs of obesity in SAT, 4 mRNAs (ENO2, YY1AP1, FAP, IL10RB) and 1 miRNA (hsa-miR-425) were found." (PMID 34621242, 2021). "For DE RNAs of obesity-related ccRCC in SAT, 4 mRNAs (ENO2, YY1AP1, FAP, IL10RB) and 1 miRNA (hsa-miR-425) were eligible for the following risk score analyses." (PMID 34621242, 2021).
autism (5 papers, 2011 to 2019). Persistent deficits in social interaction and communication and interaction as well as a markedly restricted repertoire of activity and interest as well as repetitive patterns of behavior. "Our findings indicate that downregulation of ENO2 may be associated with a subset of autism; however, it remains an open question of whether the ENO2 gene is a key component in brain development, and if it is differentially expressed in the embryo or fetal tissues at early stages of gestation." (PMID 24737292, 2014). "Ninety-six pairs of autism vs. normal control samples were subjected to quantitative BSP analysis of methylation of the ENO2 gene promoter region." (PMID 24737292, 2014). "Moreover, a recent study found ENO2 hypermethylation in autism alongside with decreased transcription and translation of this gene." (PMID 31097004, 2019). "Further confirmation with well-diagnosed and well-characterized larger size of autism cases would be necessary to assure that hypermethylation of ENO2 could be applied as a clinical biomarker for early detection of autism." (PMID 24737292, 2014).
hepatocellular carcinoma (5 papers, 2019 to 2022). A malignant tumor that arises from hepatocytes. "In this study, we first proposed that the abnormally high expressions of ENO2 and PPFIA4 was related to the poor prognosis of hepatocellular carcinoma, though they had been experimentally reported in other cancers." (PMID 36362375, 2022). "Up-regulation of Sema3A expression promoted tumor growth and tumor progression in a hepatocellular carcinoma (HCC) mouse model by enhancement of the expression of CapG, galectin-3, enolase 2 and Epithelial cell adhesion molecule (EpCAM)." (PMID 30696103, 2019). "We obtained a prognostic signature including eight hypoxia genes (ENO2, KDELR3, PFKP, SLC2A1, PGF, PPFIA4, SAP30, and TKTL1) and further established a hypoxia-related prognostic ceRNA network including 17 lncRNAs, six miRNAs, and seven mRNAs for hepatocellular carcinoma." (PMID 36362375, 2022).
teratoma (5 papers, 2007 to 2025). A non-seminomatous germ cell tumor characterized by the presence of various tissues which correspond to the different germinal layers (endoderm, mesoderm, and ectoderm). "We were able to detect two proteins, enolase-2 and angiopoietin-1, which showed consistent concentration increases over time in three out of four animals with confirmed teratomas." (PMID 26777057, 2016). "Whereas relative lower expression level of tumorigenesis genes Eno2, Nes, CD34 and Afp in Mst-/- EBs than wild type EBs may be one of the reasons that Mst-/- ES cells cannot grow teratoma." (PMID 24224013, 2013).
bladder cancer (4 papers, 2021 to 2023). "STAT3 has been shown to affect cellular metabolism, through increased glucose consumption, and lactate production in bladder cancer, through increased transcription of LDHA, ENO2, HK2, and IGFBP3." (PMID 36230984, 2022). "Overexpressed GSDMB promoted cancer cell growth via interacting with STAT3 to elevate the phosphorylation level of STAT3, which increased the expression of HK2, LDNA, ENO2, and IGFBP3 to enhance the glycolysis of bladder cancer cells." (PMID 34326684, 2021).
Huntington disease (4 papers, 2018 to 2024). Huntington disease (HD) is a rare neurodegenerative disorder of the central nervous system characterized by unwanted choreatic movements, behavioral and psychiatric disturbances and dementia. "In contrast, decreased proteins were found in glycolysis (Eno2, Pgk1, and Tdh3), Huntington’s disease (Tdh3), isoleucine biosynthesis (Ilv5) and valine biosynthesis (Ilv5)." (PMID 31973232, 2020).
pancreatic ductal adenocarcinoma (4 papers, 2020 to 2025). An infiltrating adenocarcinoma that arises from the epithelial cells of the pancreas. "Enolase 2 (ENO2) is a key glycolytic enzyme in the metabolic process of glycolysis, but its potential function in pancreatic ductal adenocarcinoma (PDAC) is unclear." (PMID 32398667, 2020).
prostate adenocarcinoma (4 papers, 2016 to 2024). "NK1R was highly expressed in NE-like cell lines PC-3 and DU145, both positive of NE markers (CgA and ENO2) and negative of AR/PSA; in contrast, in AR-positive prostate adenocarcinoma cell line LNCaP and 22Rv1, NK1R expression is much lower and NE markers are marginal." (PMID 37385990, 2023).
amyotrophic lateral sclerosis (3 papers, 2018 to 2026). Amyotrophic lateral sclerosis (ALS) is a neurodegenerative disease characterized by progressive muscular paralysis reflecting degeneration of motor neurons in the primary motor cortex, corticospinal tracts, brainstem and spinal cord. "Previous data suggested that Miro1CKO mice ablated with Eno2-Cre develop motor neuron disease (amyotrophic lateral sclerosis)-like phenotypes." (PMID 41386992, 2026).
cervical cancer (3 papers, 2021 to 2024). A primary or metastatic malignant neoplasm involving the cervix. "Enolase 2 (ENO2) and thymidylate synthetase (TYMS) are found to be upregulated in cervical cancer transcription datasets." (PMID 34790674, 2021).
Clear Cell Renal Cell Carcinoma (3 papers, 2021 to 2025). "Enolase-2 was increased in PSCs with CCK-BR-KO and has recently been found to promote ferroptosis and inhibit glycolysis in clear cell renal cell carcinoma by regulating Hippo-YAP1 signaling." (PMID 41373844, 2025).
diabetic retinopathy (3 papers, 2017 to 2021). "ENO2 or NSE is readily secreted into the cerebrospinal fluid and blood after tissue injury and is related to diabetic retinopathy." (PMID 28812028, 2017).
glaucoma (3 papers, 2021 to 2025). Increased pressure in the eyeball due to obstruction of the outflow of aqueous humor. "The expression of 3 biomarkers in the GSE9944 dataset suggested that NAMPT and ADH1C were up-regulated and ENO2 down-regulated in glaucoma samples." (PMID 35366826, 2022).
head and neck squamous cell carcinoma (3 papers, 2024 to 2025). A squamous cell carcinoma that arises from any of the following anatomic sites: lip and oral cavity, nasal cavity, paranasal sinuses, pharynx, larynx, and salivary glands. "In head and neck squamous cell carcinoma (HNSCC), Enolase 2 (ENO2), a crucial glycolytic enzyme in cancer metabolic process, directly interacts with PKM2, preventing its degradation while enhancing its glycolytic activity." (PMID 41169372, 2025). "In addition, ENO2 has been found to interact with PKM2, preventing PKM2 ubiquitin-mediated proteasomal degradation and regulating PKM2-driven CCND1-mediated cell cycle progression, proliferation, and glycolysis in head and neck squamous cell carcinoma (HNSCC)." (PMID 39061144, 2024).
Insulin resistance (3 papers, 2011 to 2025). Increased resistance towards insulin, that is, diminished effectiveness of insulin in reducing blood glucose levels. "Finally, in metabolism we found concordant upregulation of oxidative stress-response genes such as Gfpt2 and glycolysis related genes such as Pgk1, with downregulation of gluconeogenesis gene Eno2, and diacylglycerol kinases Dgka and Dgkh, important in fatty acid metabolism and insulin resistance." (PMID 21696628, 2011).
autoimmune disease (2 papers, 2011 to 2019). A disorder resulting from loss of function or tissue destruction of an organ or multiple organs, arising from humoral or cellular immune responses of the individual to their own tissue constituents. "Enolase1 and enolase 2 are autoantigen targets in post-streptococcal autoimmune disease of central nervous system." (PMID 21445266, 2011).
diffuse large B-cell lymphoma (2 papers, 2016 to 2024). "Previous works determined that up-regulation of enolase 2 (ENO2) in diffuse large B-cell lymphoma (DLBCL) cells can promote macrophages to an M2-like phenotype, thereby consequently promoting the progression of DLBCL." (PMID 38250157, 2024).
endothelial dysfunction (2 papers, 2023 to 2024). In vascular diseases, endothelial dysfunction is a systemic pathological state of the endothelium (the inner lining of blood vessels) and can be broadly defined as an imbalance between vasodilating and vasoconstricting substances produced by (or acting on) the endothelium. "As excessive ROS generation at the site of inflammation causes endothelial dysfunction and tissue injury, therefore we wanted to evaluate the expression level of neuronal injury marker, Enolase-2 in postnatal brain at PD7 and PD90." (PMID 37693917, 2023).
leukaemia (2 papers, 2022 to 2023). "SATB1 (top seven) plays a critical role in relevantpathways conferring anti-tumour immunity.Lastly, knockdown of ENO2 (top nine) has been associated with a reduction on thesurvival rate of leukaemia cells." (PMID 36124841, 2022).
non-Hodgkin lymphoma (2 papers, 2016 to 2024). Distinct from Hodgkin lymphoma both morphologically and biologically, non-Hodgkin lymphoma (NHL) is characterized by the absence of Reed-Sternberg cells, can occur at any age, and usually presents as a localized or generalized lymphadenopathy associated with fever and weight loss. "Our study, supporting the use of five approaches, including TMT, gene ontology (GO), Reactome, KEGG pathway, and molecular docking analyses, suggests that DEPs, Myh3, Eno2, and H4c11 may be three novel biomarkers or therapeutic targets for non-Hodgkin lymphoma." (PMID 39861068, 2024).
olfactory neuroblastoma (2 papers, 2019 to 2022). An olfactory neuroblastoma arising in the paranasal sinus. "As expected, differential expression analysis in comparison to normal sinonasal tissue revealed overexpression of classical neuronal proteins in olfactory neuroblastomas (e.g., ENO2)." (PMID 36443295, 2022).
bladder tumor (1 paper, 2022). "Furthermore, results from GSE13507 revealed that the mRNA level of ENO1 and ENO2 were increased in bladder tumor tissues as compared to normal counterparts." (PMID 35836227, 2022). "Consistently, data from TIMER database manifested that mRNA expression of ENO1, but not ENO2 and ENO3, was upregulated in bladder tumor tissues." (PMID 35836227, 2022).
heroin dependence (1 paper, 2016). Physical and psychological dependence on the drug heroin. "In this analysis, we found that the 4-gene model that contained JUN, CEBPB, ENO2, and PRKCB genes had an accuracy rate of 85.5% in the prediction of heroin addiction in this dataset." (PMID 27495086, 2016). "Our classification analysis identified JUN, CEBPG, ENO2, and PRKCB as the key gene expression signatures for a subdivision of heroin dependence and controls." (PMID 27495086, 2016).
laryngeal carcinoma (1 paper, 2022). Carcinoma that arises from the laryngeal epithelium. "Three genes, lactate dehydrogenase A (LDHA), enolase 2 (ENO2) and macrophage migration inhibitory factor (MIF), may be involved in lipid metabolism in laryngeal cancer cells." (PMID 36042480, 2022).
Simpson-Golabi-Behmel syndrome (1 paper, 2020). Simpson-Golabi-Behmel syndrome is a rare X-linked multiple congenital anomalies syndrome, characterized by pre- and postnatal overgrowth, distinctive craniofacial features, variable congenital malformations, organomegaly and an increased tumor risk. "Indeed, Que (25 μM) was added to the cell cultures and it reduced the accumulation fatty acids and their metabolites in human Simpson Golabi Behmel Syndrome (SGBS) preadipocytes, probably through the Enolase 2 gene that is vital for the conversion 2-phosphoglycerate into phosphoenolpyruvate." (PMID 32848878, 2020).